CYP1B1 (cytochrome P450 family 1 subfamily B member 1)
Diseases named in the same sentence as CYP1B1 in open-access papers (continued):
Sharing a sentence is not in itself a finding about the gene and the disease.
breast carcinoma (continued). "ERCC1/CYP1B1 combination might be of particular interest to predict response to NCT in breast cancer and particularly to help NCT indication for ER+ breast tumors." (PMID 26180747, 2015). "Multivariate analysis revealed that ERCC1 (Asn118Asn) combined to CYP1B1 (Leu432Val) might be of particular interest as predictive markers for NCT in breast cancer." (PMID 26180747, 2015). "Importantly, the expression of the AhR and downstream gene targets such as CYP1B1 are increased in human and rodent mammary tumors." (PMID 26715507, 2015). "The overexpression of CYP1B1 has been reported in mammary tumours and breast cancer." (PMID 24270600, 2014). "Inverse correlation between CYP1B1 and miR-27b expression levels in breast cancer tissues has been evidenced; thereby suggesting that CYP1B1 overexpression in tumor tissues could be a consequence of miR-27b downregulation." (PMID 26056584, 2014). "We set out to ascertain whether there might be an association between polymorphisms in exon 2 (codon 119, G→T) and exon 3 (codon 432, G→C) of CYP1B1 and breast cancer in a Chinese Han population in the rural region of Ningxia." (PMID 20212917, 2010). "The inconsistent relationships between CYP1B1, COMT, and breast cancer risk seen across epidemiology studies may reflect divergent risk associated with variable environmental E2 exposures." (PMID 20435547, 2010). "Maternal TCDD exposure also increased mammary tumor Cyp1b1 expression." (PMID 20435547, 2010). "There appear to be no significant overall association between the CYP1B1 Val/Leu variant and breast cancer risk in Caucasian populations in a recent meta-analysis." (PMID 19208203, 2009). "Meta-analysis of these studies in African-American and mixed populations showed no overall significant risk associated with the CYP1B1 Val432Leu polymorphism in breast cancer susceptibility in these populations." (PMID 19208203, 2009). "As CYP1B1 can inactivate the prostate cancer dug flutamide and is also induced in breast cancer cells after treatment with docetaxel, it may have an important function in the development of resistance to chemotherapy." (PMID 18797454, 2008). "Overall, CYP1B1 has a variety of functions in both the treatment and development of breast cancer." (PMID 18797454, 2008). "The results indicate that specific polymorphisms in the CYP1B1, ESR1, and ESR2 genes may play a role in progression of BBD to breast cancer among Caucasian women." (PMID 16808847, 2006). "The findings of this study indicate that specific polymorphisms in the CYP1B1, ESR1, and ESR2 genes may play a role in progression of BBD to breast cancer among Caucasian women." (PMID 16808847, 2006). "All of the polymorphisms examined were in Hardy-Weinberg equilibrium among women not developing breast cancer, with the exception of the CYP1B1 Ile462Val polymorphism (p-value = 0.02)." (PMID 16808847, 2006). "The CYP1B1 Val432Leu polymorphism has been associated with breast cancer in an Asian study but not in two studies of Caucasians." (PMID 15987428, 2005). "The results suggest that the CYP19 Arg264Cys polymorphism modifies breast cancer risk (OR=1.5, 95% CI=1.1–2.2), especially in association with alcohol consumption (P for interaction=0.04), whereas the CYP1B1 Leu432Val polymorphism appears to play no role here." (PMID 12618873, 2003). "Thus, metformin decreases CYP1A1 and CYP1B1 expression in breast cancer cells by suppressing the AhR signaling pathway and may act as a potential chemopreventive agent against CYP1B1- and CYP1A1-mediated carcinogenesis and cancer progression." (PMID 41440753, 2025). "Thus, protective effect of CYP1B1-polymorphisms with doxorubicin and paclitaxel basedchemotherapy induced N-HEM toxicity and CYP2C9- polymorphisms with paclitaxel induced body ache and CYP1A1-polymorphisms with peripheralneuropathy in breast cancer patients." (PMID 40092865, 2024).
breast carcinoma (continued). "Thus, CYP1B1 modulation may affect multiple mechanisms that provide chemotherapeutic benefit in breast cancer treatment." (PMID 36077068, 2022). "CYP1B1 inhibitors in combination with chemotherapeutic drugs may provide a novel targeted and effective approach to adjuvant or neoadjuvant therapy against certain forms of highly metastatic breast cancer." (PMID 36077068, 2022). "Thus, an observed increase in the activity of CYP1B1 may result from its role in the activation of carcinogenic compounds and the induction of hormone-dependent neoplasms, including breast cancer." (PMID 35008866, 2021). "Considering that CYP1B1 contributes to both the carcinogenic activation of environmental chemicals and the bio-transformation of endogenous estrogens, its role in the initiation and progression of hormone-dependent malignancies, including breast cancer, has been suggested." (PMID 31370872, 2019). "Here, we have provided novel insights on the crosstalk that may occur between AHR and GPER upon exposure to 3MC, toward the up-regulation of CYP1B1 and cyclin D1 expression as well as the proliferative effects observed in breast cancer cells and main components of the tumor microenvironment as CAFs." (PMID 31370872, 2019). "In addition, CYP1B1 is overexpressed in different tumors including breast cancer." (PMID 29290975, 2017). "Thus, GPER may be included among the transduction mediators through which estrogens generate a feed-forward loop driving CYP1B1 expression and its metabolic action toward breast cancer development." (PMID 29290975, 2017). "Thus, linking pesticide exposure to this imbalanced ratio in favor of the CYP1B1 enzyme would provide direct evidence that pesticides may play a role in the early steps of breast cancer development." (PMID 25257533, 2014). "The CYP1B1 gene polymorphisms do not influence breast cancer risk overall but may modify the risk after long-term menopausal hormone use." (PMID 17316436, 2007). "SFN reduced CYP1A1 protein level equally in nontumorigenic MCF10A breast cells, ER(+) MCF7, and ER(−) MDA-MB-231 breast cancer cells, but the increased level of CYP1A2 and the decreased level of CYP1B1 expression were found only in MCF10A cells." (PMID 40807256, 2025). "Importantly, previous works have demonstrated that CYP1B1 is overexpressed in breast cancer cells and that leptin upregulates CYP1B1 mRNA and protein expression in breast cancer, thus suggesting that increase in CYP1B1 expression may be one of the mechanisms for the pro‐tumoral activity of leptin." (PMID 39806854, 2025). "Although CYP1B1 is considered to have an inhibitory effect on many malignant tumors, HIF-1α can affect the expression of CYP1B1 by activating estrogen receptor α in breast cancer." (PMID 40989158, 2025). "According to alcohol metabolism-involved genes, three were up-regulated (ITGA5, CBS, and SOD2), and six were down-regulated (XDH, XRCC1, MTHFR, CYP1B1, XPC, and GSTP1) among women who died for breast cancer." (PMID 39125744, 2024). "AMPK was activated by 2-hydroxy-6-tridecylbenzoic acid and in turn upregulated the expression of cytochrome P450 1B1 (CYP1B1), as well as reversing the EMT processes in breast cancer cells." (PMID 36677797, 2023). "HA/PEI NPs effectively overcome the CYP1B1-mediated MDR in breast cancer and provide a promising strategy for the treatment of MDR breast cancer." (PMID 36091467, 2022). "Breast cancer can be prevented by eating foods that change the activity of certain cytochrome P450 enzymes, including CYP1A1, CYP1A2, CYP1B1, CYP2B6, CYP3A4, CYP19A1, and CYP24A1." (PMID 36571647, 2022). "Docetaxel, a commonly used chemotherapeutic drug, is inactivated by the action of CYP1B1, an enzyme overexpressed by MDR breast cancer cells." (PMID 35645591, 2022).
breast carcinoma (continued). "Our findings that CYP1B1 KD can increase chemosensitivity supports the idea that therapeutic targeting of this enzyme, in combination with chemotherapeutic drugs, may provide a novel targeted approach to adjuvant or neoadjuvant therapy against certain forms of highly metastatic breast cancer." (PMID 36077068, 2022). "In breast cancer, the stability and expression of METTL14 are positively regulated by LNC942, which elevates the m6A content in downstream targets CXCR4 and CYP1B1, stabilizes protein expression and translation, and further promotes tumorigenesis." (PMID 34904301, 2022). "Alternatively, miR-200c-3p modulates the expression of metabolic enzyme cytochrome P450 1B1 (CYP1B1) and transcription factor SOX2 in renal cell carcinoma and breast cancer, respectively." (PMID 34439151, 2021). "CYP1B1, a member of the CYP superfamily, plays a critical role in oxidative metabolism and promotes the development of breast cancer." (PMID 34604236, 2021). "Three genes were up-regulated (i.e., ITGA5, CBS, and SOD2), while six were down-regulated (i. e, XDH, XRCC1, MTHFR, CYP1B1, XPC, and GSTP1) among individuals who died of breast cancer." (PMID 32078659, 2020). "WY-14643, a PPARα agonist, has been shown to increase the protein and mRNA levels of CYP1B1 in MCF-7 cells via PPARα-dependent mechanism, playing a critical role in the progression of human breast cancer." (PMID 33185690, 2020). "CYP1B1 inhibitors have also been shown to enhance the chemotherapeutic effects of DOX in several cancer cell lines including lung cancer, breast cancer, liver cancer, glioblastoma, prostate cancer, colorectal cancer, gastric cancer, and leukemia." (PMID 33185690, 2020). "Estrogens play an important role in breast cancer, probably by stimulating cellular proliferation and oxidative metabolism mediated by various cytochrome P450 (CYP) enzymes such as CYP1A1 and CYP1B1." (PMID 31380268, 2019). "In this study, we investigated the effects of WY-14643, a peroxisome proliferator-activated receptor α (PPARα) agonist, on CYP1B1 expression and the related mechanism in MCF7 breast cancer cells." (PMID 31775380, 2019). "CYP1A1 is particularly implicated in lung, colorectal, breast, and prostate cancers, CYP1B1 in hormone dependent cancers of the prostate, breast, and endometrium, and CYP1A2 in colorectal, lung, and breast cancers." (PMID 29462868, 2018). "Overall, these data suggest that GPER and CYP1B1 are involved in the stimulatory effects exerted by E2 and G-1 in MDA-MB-231 breast cancer cells both in vitro and in vivo." (PMID 29290975, 2017). "We previously demonstrated that constitutively active AHR in breast cancer lines preferentially drives Cyp1b1 expression while an exogenous ligand, e.g. DMBA, tends to induce greater fold-increases in Cyp1a1 than Cyp1b1." (PMID 26984638, 2016). "CYP1A1, AHR, AR, CYP1A, CYP1B1 and PTGS2 genes are common in both PCB-gene and PCB-gene-breast cancer groups." (PMID 26512648, 2015). "The upregulation of Ahr and Cyp1b1 were paralleled by increased Brca-1 CpG methylation, and reduced expression of BRCA-1 and ERα in mammary tumors induced with DMBA." (PMID 26715507, 2015). "A study conducted in ER-positive MCF-7 breast cancer cells suggested TRX to be involved in the constitutive expression of CYP1B1 and the dioxin mediated induction of CYP1B1." (PMID 21967738, 2011). "Heterozygosity for the CYP1B1 M1 genotype (CYP1B1 M1 [Val/Leu]) was associated with a significant 59% increased risk of breast cancer (OR = 1.59, 95% CI 1.01–2.58) while homozygosity for the genotype (CYP1B1 M1 [Leu/Leu]) conferred a non-significant 51% increased risk of breast cancer." (PMID 19208203, 2009). "A cohort study was conducted to examine the role of genetic polymorphisms in three estrogen metabolizing enzymes (COMT, CYP1A1, CYP1B1) and the two estrogen receptors (ESR1, ESR2) in the progression of benign breast disease (BBD) to breast cancer." (PMID 16808847, 2006).
breast carcinoma (continued). "On the other hand, nobiletin and polymethoxyflavone were shown to induce their own metabolism, which may affect their cytostatic effect in MCF7 breast cancer cells, via CYP1A1 and CYP1B1 upregulation." (PMID 40807256, 2025). "In the case of breast cancer cells, the CYP1A1 protein level was slightly reduced by 3,4,2′-trimethoxy (3MS) and 3,4,2′,4′-tetramethoxy (4MS), and the CYP1B1 expression was decreased as a result of the treatment with 4MS, but only at the transcript level in MDA-MB-231 cells." (PMID 40807256, 2025). "Therefore, it is of interest to assess the correlation ofCYP1A1, CYP1B1, CYP2C genotypes with treatment efficacy and clinical outcomes in breast cancer patients administered with doxorubicinand paclitaxel based chemotherapy." (PMID 40092865, 2024). "Besides breast cancer, overexpression of LncRNA UCA1 also accelerated Acute myeloid leukemia (AML) development by regulating METTL14-mediated CXCR4 and CYP1B1 mRNA." (PMID 37365581, 2023). "Interestingly, GPER is reported to regulate CYP1B1 expression in ER- breast cancer and modulation of both GPER and CYP1B1 alter tumor cell growth in vitro and in vivo." (PMID 36077068, 2022). "It has been reported that the abnormal expression of STAT1, ESR1, CYP1B1, FN1 and UGT1A family genes is closely related to breast cancer and TAM multidrug resistance, while the relationship between AKR1 family and breast cancer and TAM resistance has not been studied." (PMID 34886806, 2021). "If true, the interactions between acrylamide and HSD3B SNPs for ovarian cancer and between acrylamide and the CYP1B1 and CYP11A1 SNPs for breast cancer in the current study give some indications that acrylamide may interfere with progesterone metabolism." (PMID 29445914, 2019). "The constitutive mRNA expression and cellular content of CYP1A1 and CYP1B1, AhR-regulated genes, were markedly higher in CSCs more than differentiating non-CSCs of five different human breast cancer cells." (PMID 28103884, 2017). "The relatively high expression of all assayed enzymes was shown in MDA-MB-231 breast cancer cells, lack of cancer cell specific CYP1B1 protein was discovered in LOVO colorectal cells." (PMID 23873331, 2013). "Thus, the breast carcinoma cell line MDA-MB-468 constitutively expresses CYP1A1 and, after induction, increases CYP1A1 levels and expresses low levels of CYP1B1." (PMID 18454852, 2008). "However, low levels of CYP1B1 and CYP1A1 activity have been reported for similar breast cancer cell lines such as MDA-MB-436, MDA-MB-231, MDA-MB-157, and T47 in the absence of TCDD, whereas in its presence the activity was largely augmented." (PMID 18454852, 2008). "Moreover, overexpression of CYP1B1 is not known to activate the AHR, and treatment of breast cancer cell lines with 4-hydroxyestradiol, the primary estrogen product of CYP1B1, results in effects similar to ectopic CYP1B1 expression." (PMID 36077068, 2022). "Molecular modeling showed CYP1B1 favored a ring orientation to the heme group compared to CYP1A1; therefore, activation of CYP1B1 and conversion of luteolin to the hydroxylated form may enhance antiproliferative activity against breast cancer." (PMID 34594472, 2021). "The breast tissue from women with breast cancer also demonstrated greater expression of the estrogen-activating enzymes CYP19 and CYP1B1, compared to women without breast cancer, who exhibited greater expression of the estrogen-protective enzymes COMT and NQO137." (PMID 30854528, 2017). "As miR-27b exhibits lower levels in breast cancer, the miR-27b mediated translational inhibition of CYP1B1 expression may account for the tumor-specific expression of CYP1B1 at protein level rather than mRNA level in breast cancer." (PMID 27834829, 2016). "Overall, these analyses of this set of clinical data showed a negative correlation of expression of CYP1B1 and CLDN7 in breast cancer, consistent with our findings in CL TNBC." (PMID 36077068, 2022).
breast carcinoma (continued). "In MCF-7 human breast cancer cells, chrysoeriol did not affect the CYP1A1 and CYP1B1 gene expression, but significantly inhibited the production of 4-MeOE2 without any effects on the formation of 2-MeOE2." (PMID 34462889, 2021). "Of note, E2 and the selective GPER agonist G-1 induced CYP1B1 mRNA and protein levels in cell contexts lacking ER but expressing GPER as SkBr3 breast cancer cells, CAFs and met-CAFs." (PMID 29290975, 2017). "Short-term treatment with docetaxel induced CYP1B1 mRNA expression in MDA 453 and BT-20 breast carcinoma cells, but not in MCF-7 cells." (PMID 18212750, 2008). "Moreover, rodent and human mammary tumors overexpress constitutively active AHR, which is characterized by elevated CYP1B1 but not CYP1A1 mRNA." (PMID 31652854, 2019). "Further evidence of imbalance in estrogen homeostasis derives from the greater expression of estrogen-protective enzymes, COMT and NQO1, in women without breast cancer and greater expression of estrogen-activating enzymes, CYP19 and CYP1B1, in breast tissue of women with breast cancer." (PMID 26979321, 2016). "We showed that AF could activate a DRE-driven luciferase reporter and induce expression of CYP1A1 and CYP1B1 in AF-sensitive, ERα-negative MDA-MB-468 human breast cancer cells." (PMID 24885022, 2014). "In particular, it was reported that luteolin could be metabolized into 6 hydroxyluteolin by recombinant CYP1B1, but not by CYP1A1 and CYP1A2, and that hydroxylation of luteolin at the 6 position of the A ring is crucial for the antiproliferative activity in breast cancer cells." (PMID 34594472, 2021).